RN7SKP28 (RN7SK pseudogene 28)
Gene: Miscellaneous RNA gene on chromosome 4 (96,348,734 to 96,349,038, reverse strand). Ensembl gene ENSG00000201640.
Homologues: Orthologues: chimpanzee 7SK (98% identical), guinea pig 7SK (45% identical). Paralogues in human: RN7SKP9 (78% identical), 7SK (76% identical), RN7SKP184 (76% identical), RN7SKP37 (76% identical), RN7SKP180 (76% identical), RN7SKP189 (75% identical), RN7SKP237 (75% identical), RN7SKP170 (75% identical), RN7SKP255 (75% identical), RN7SKP146 (74% identical), RN7SKP163 (74% identical), RN7SKP203 (74% identical), and 284 more.